IL13 (interleukin 13)
Diseases named in the same sentence as IL13 in open-access papers (continued):
Sharing a sentence is not in itself a finding about the gene and the disease.
atopic dermatitis (continued). "The role of IL-13 on vaccinia infection has been studied in the context of atopic dermatitis and its effect on vaccinia growth in keratinocytes has been reported." (PMID 21931646, 2011). "T cells and mast cells are important sources of IL-13 in skin lesions from patients with atopic eczema." (PMID 22013915, 2011). "Th2 cells release cytokines, such as IL-4, IL-5, and IL-13, in allergic inflammation and atopic dermatitis." (PMID 21303540, 2011). "IL-13 is expressed in acute and chronic lesions and in unaffected skin from patients with atopic eczema." (PMID 22013915, 2011). "A combination of IL-4 and IL-13 was used as a Th2 cytokine mix, to resemble the atopic dermatitis cytokine microenvironment of active lesions." (PMID 18523683, 2008). "Tralokinumab, an anti-IL-13 antibody, is effective for atopic dermatitis (AD); however, its long-term (> 1 year) effectiveness specific to each anatomical site is unknown in real-world settings." (PMID 41489176, 2026). "One possibility is that IL-31 blockade induces compensatory upregulation of Th2 cytokines such as IL-4 and IL-13, which could partly explain the development or exacerbation of eczematous lesions, including atopic dermatitis." (PMID 41464561, 2025). "This could be due to saturation of the IL13 pathway in these patients, or it could indicate differences in epithelial activation according to atopic dermatitis status." (PMID 40662227, 2025). "Dupilumab, a fully human monoclonal antibody targeting the interleukin-4 receptor alpha (IL-4Rα), blocks both IL-4 and IL-13 signaling and is approved for several type 2 inflammatory conditions, including atopic dermatitis, asthma, and chronic rhinosinusitis with nasal polyposis." (PMID 40981278, 2025). "The role of interleukins IL-4, IL-5, IL-10, IL-13 and IL-33 in atopic dermatitis." (PMID 40771803, 2025). "GSVA revealed MC IL‐4 + IL‐13 signatures enriched in atopic dermatitis and psoriasis, IFNγ in COVID‐19 infection and cystic fibrosis, IL‐33 in COVID‐19 and chronic obstructive pulmonary disease (COPD) and TGFβ in pulmonary fibrosis (PF) and chronic rhinosinusitis." (PMID 40926620, 2025). "Atopic dermatitis (AD) is a chronic inflammatory skin disease primarily treated with corticosteroids and dupilumab, a monoclonal antibody targeting interleukin (IL)-4 and IL-13." (PMID 40999478, 2025). "Thus, for patients who develop irBP as a side effect of cancer immunotherapy, IL-4 and IL-13 inhibitors such as dupilumab, so far approved to treat atopic dermatitis and prurigo nodularis, appear to be a promising new treatment option." (PMID 40507326, 2025). "Studies have reported elevated levels of inflammatory cytokines, such as IL-4 and IL-13 and periostin, in the tear fluid of atopic dermatitis patients, which may exacerbate allergic responses on the ocular surface." (PMID 40718327, 2025). "However, it is surprising that IL-4 and IL-13, while being key drivers of atopic dermatitis pathology, suppress 5-LO/ALOX5 expression." (PMID 41296013, 2025). "In atopic dermatitis, IL-13 and IL-4 produced by Th2 cells are known to promote the pathology, and monoclonal antibody preparations targeting IL-13/IL-4 receptors have become common treatments for atopic dermatitis." (PMID 39562488, 2025). "Our findings indicate that biologics may influence Th2 immune responses, especially IL-13, which showed significantly elevated levels in biotreated patients, particularly those with allergic rhinitis (AR) and atopic dermatitis (AD)." (PMID 40364125, 2025). "Similarly, the JAK-STAT signaling pathway is utilized by IL-4, IL-5, and IL-13 to induce Th2 immunity in Atopic Dermatitis." (PMID 39119011, 2024). "It was reported that Ech suppressed IL-4 and IL-13 in the atopic dermatitis model." (PMID 37750936, 2024).
atopic dermatitis (continued). "Dupilumab is a monoclonal antibody that inhibits interleukin-4 (IL-4) and interleukin-13 (IL-13) signaling and is used in the treatment of moderate-to-severe atopic dermatitis (AD) in those six months or older who are uncontrolled on or cannot tolerate topical treatments." (PMID 39834978, 2024). "While CSU and atopic dermatitis (AD) can be clinically distinguished by specialist clinicians, they share significant similarities in their inflammatory mechanisms, particularly in the role of pro-inflammatory cytokines like IL-4, IL-5, IL-13, and IL-31." (PMID 38396704, 2024). "Further, CM also suppressed the levels of IL-4 and IL-13 in Th2 cells, suggesting that CM may have therapeutic potential as a drug for atopic dermatitis." (PMID 38791236, 2024). "In dogs with atopic dermatitis, serum IL‐13 increased more than IL‐4, suggesting that IL‐13 may play an important role in the development of the atopic response, compared to IL‐4." (PMID 38648253, 2024). "The targeted IL-13 inhibitors (tralokinumab, lebrikizumab, cendakimab, and eblasakimab) have been approved for the treatment of moderate to severe atopic dermatitis, offering treatment efficacy, safety, persistence over time, and a significant improvement in pruritus and quality of life." (PMID 38672221, 2024). "In addition, dupilumab is effective for chronic rhinosinusitis with nasal polyps and for atopic dermatitis, and IL-4/IL-13 blocking is expected to suppress allergen sensitization, including transcutaneous sensitization and atopic march." (PMID 38785953, 2024). "Additionally, DNCB-induced atopic dermatitis mice exhibited significantly increased Th2 (IL-4 and IL-13), Th1 (IFN-γ), and Th17 (IL-17A) cytokine mRNA levels in the cervical lymph nodes." (PMID 38672764, 2024). "Thus, JAK inhibition likely prevents the activity of IL-4/IL-13 involved in the inflammation of atopic dermatitis as well as treats the inflammatory arthritis due to its effect on curbing the IL-23/17 pathway." (PMID 39360077, 2024). "Moreover, T2-high cytokines, IL-4 and IL-13, play a key role in the pathophysiology of skin inflammation, such as atopic dermatitis." (PMID 39188724, 2024). "However, antimicrobial peptides have been reported to induce the IL-4, IL-13, and IL-31 inflammatory pathways, which are hallmark features of atopic dermatitis, indicating that these peptides might function as a double-edged sword in the pathogenesis of atopic dermatitis." (PMID 37298299, 2023). "Nectin-1 distribution in atopic dermatitis skin and in IL-4/IL-13-treated human skin." (PMID 37289055, 2023). "Moreover, calcitriol treatment reversed the decrease in the expression of skin barrier-related proteins and decreased the expression of inflammatory cytokines such as interleukin (IL)-13 and IL-33 in mice with atopic dermatitis." (PMID 37298299, 2023). "On the other hand, excessive intake of linoleic acid may aggravate type 2 immune response as seen in atopic dermatitis with IL-4 and IL-13 overproduction." (PMID 37492568, 2023). "In primary keratinocytes, atopic dermatitis cytokines (IL-4, IL-13 and IL-31) significantly decreased mRNA expression of the barrier structure protein filaggrin (FLG) without histamine (0.3 ± 0.06-fold, p < 0.001) and in combination with histamine (0.24 ± 0.04-fold; p < 0.001)." (PMID 36615633, 2023). "Atopic dermatitis, a significant risk factor for CHE, has a complex pathophysiology with the predominant involvement of Th2 cells and certain cytokines, such as IL-4 and IL-13, associated with skin barrier defects." (PMID 38203533, 2023). "Dupilumab inhibits the IL-4/IL-13 signaling pathway to reduce itching and itching in atopic dermatitis, which may reduce the release of CCL20 from keratinocytes and also reduce Th17 cell infiltration." (PMID 35069008, 2022).
atopic dermatitis (continued). "One example is lebrikizumab, a high-affinity anti-IL13 that has been shown to have efficacy in a phase 2b study of moderate to severe atopic dermatitis in adults and may be a candidate for future studies in food allergy." (PMID 35434724, 2022). "In addition, a group of IL-5 and IL-13-producing resident ILC2s have been observed in the skin of healthy humans and increased in samples from patients with atopic dermatitis, as well as in a murine model of the same condition." (PMID 34759931, 2021). "While having effects on many different cell types, the main functions of the IL-4 and IL-13 pathways are the production of human immunoglobulin E and T-helper cell differentiation, which then brings on the clinical symptoms of atopic dermatitis, allergic rhinitis, and allergic asthma." (PMID 34948449, 2021). "IL-4 and IL-13 are classical Th2 cytokines, with a documented role in atopic dermatitis and asthma." (PMID 33544244, 2021). "This IL‐13–ΔNp63 axis may constitute a vicious cycle, partly explaining the chronicity of atopic dermatitis." (PMID 33792188, 2021). "Notably, a monoclonal antibody directed against the IL-4 receptor α subunit, blocking IL-4 and IL-13 signaling, has been evaluated in patients with atopic dermatitis, with significant improvement in disease severity." (PMID 34938293, 2021). "Among them, dupilumab, a fully humanized IgG4 monoclonal antibody, targets IL-4/IL-13 signaling and displays strong efficacy as add-on therapy in severe uncontrolled asthmatic patients as well as in the T2 diseases atopic dermatitis and chronic rhinosinusitis with nasal polyps." (PMID 34572281, 2021). "The IL-4 and IL-13 cytokine pathways play integral roles in stimulating IgE inflammation, with the IL-4 cytokine being a major cytokine in the etiology of thunderstorm asthma, atopic dermatitis, and allergic rhinitis." (PMID 34948449, 2021). "The overproduction of IL-13 is one of the mainsprings of the pathogenesis of atopic dermatitis." (PMID 34684016, 2021). "Other cytokines, such as IL-4, IL-13, IL-31 and IL-33 play a key role in the pro-inflammatory and anti-inflammatory signaling pathways in patients suffering from inflammatory skin diseases such as psoriasis or atopic dermatitis." (PMID 33467067, 2021). "Interleukin (IL)-13 plays a key role in the pathogenesis of atopic dermatitis (AD)." (PMID 32922169, 2020). "As Th2 cytokines including IL-4 and IL-13 are pathological markers of atopic dermatitis, we analyzed the levels of these cytokines to determine whether perphenazine attenuates cytokine expression." (PMID 32375285, 2020). "Furthermore, recently published results from large-scale trials confirm that elimination of IL-13 is highly effective in atopic dermatitis, an exceedingly common condition, as well as eosinophilic esophagitis." (PMID 32294982, 2020). "Along with TSLP and IL4/IL-13, CXCL10 may cause some of the symptoms of atopic dermatitis, although the role of this cytokine in the disease remains to be fully characterized." (PMID 31782733, 2019). "In the case of atopic dermatitis ILC2 have been described to be the major proinflammatory ILC subtype accountable for the production of marker cytokines like IL-13 and IL-5, cross-talk with other innate cells like basophils and dendritic cells, and finally promoting the development of TH2 cells." (PMID 31781103, 2019). "In mice with chemically-induced atopic dermatitis, potato extract alleviated the exacerbation of skin lesions by suppressing total serum level of IgE and maintaining T helper 1 (Th1; interferon-γ, and IL-12) and Th2 cytokines (IL-4 and IL-13) balance." (PMID 29495317, 2018). "Although S. aureus colonization has been strongly associated with atopic dermatitis, which is driven by Th2 responses, most components of the Th2 response such as IL-4, IL-5, and IL-13 were not induced by early colonization of S. aureus." (PMID 30185226, 2018).
atopic dermatitis (continued). "Finally, expression of IL13 in keratinocytes is sufficient to induce a disease mimicking atopic dermatitis." (PMID 27431613, 2016). "In addition, TRPA1 was upregulated in sensory neurons and TRPA1 antagonists reduced itch behavior in an interleukin 13-overexpressing transgenic model of atopic dermatitis." (PMID 27983625, 2016). "Indeed in several skin disorders (atopic dermatitis, psoriasis, sclerosis) associated with fibrotic responses and inflammation, locally increased CD8+ IL-13 producing T-cells have been identified that seemed critical players." (PMID 25803478, 2015). "Besides, it has been shown recently in an elegant study that replacement of IL-4 and IL-13 by IL-17 in a combination of several cytokines led to the switch from an atopic dermatitis-like to a psoriasis-like three dimensional in vitro model." (PMID 26656739, 2015). "Th2 cells produce IL-4, IL-5, and IL-13 and play major roles in acute atopic dermatitis." (PMID 24499290, 2013). "IL-4 and IL-13 induce immunoglobulin E (IgE) production in vitro, and their mRNA levels are strongly up-regulated in biopsy specimens of allergic contact dermatitis as well as atopic dermatitis patients." (PMID 23531535, 2013). "IL-22, TNFa, IL-4, and IL-13 combination is able to mimic an “atopic dermatitis like” state." (PMID 23193414, 2012). "Gelato and Mastorino, in their analysis of a patient who developed multiple sclerosis (MS) after starting dupilumab treatment for atopic dermatitis, hypothesized that dupilumab could induce a shift toward Th1/Th17 polarization by blocking the shared receptor subunit for IL-4 and IL-13." (PMID 39007153, 2024). "(2016) reported that IL‐13 may play an important role in the formation of atopic response, compared to IL‐4 in dogs with atopic dermatitis, in the present study, it was shown that both IL‐4 and IL‐13 cytokine responses to environmental allergens occur in dogs with atopic dermatitis." (PMID 38648253, 2024). "Therefore, miR-143 may serve as a potential prophylactic and therapeutic target in the treatment of atopic dermatitis, acting as a suppressor of IL-13-induced dysregulation of skin barrier proteins in epidermal keratinocytes." (PMID 37298095, 2023). "High IL-13 production by phytohaemagglutinin- and house dust mite allergen Der p 1-stimulated cord blood mononuclear cells has been associated with the development of atopic eczema by the age of 3 years." (PMID 22013915, 2011). "In allergic dermatitis models, neutrophils exacerbate inflammation via LTB4‐mediated CD4+ T cell recruitment and IL‐4/IL‐13 upregulation." (PMID 41583119, 2026). "IL23A, IL4, IL13, and TNFR1 are targets of medically efficacious drugs in widespread use in psoriasis and atopic dermatitis, consistent with the observed enhanced likelihood of success for polygenic disease therapeutics directed at GWAS-linked targets." (PMID 40998781, 2025). "Specifically, the cytokines that promote isotype switching (e.g., IL-4, IL-13, and IFN-γ) are only poorly to modestly expressed in necrobiotic skin when compared with other inflammatory conditions like atopic dermatitis." (PMID 39989459, 2025). "In conclusion, this study underscores the efficacy of IL-4/IL-13 inhibitors and JAK inhibitors in improving skin barrier function in atopic dermatitis patients." (PMID 39202657, 2024). "Clinical intake of DS has been reported to improve allergic skin responses by restoring mineral imbalances in atopic eczema/dermatitis syndrome, and by reducing levels of IgE and Th2 cytokines (IL4, IL6, and IL13) in allergic rhinitis." (PMID 38921545, 2024). "This systematic review aims to evaluate the restoration of skin barrier abnormalities with interleukin-4/interleukin-13 (IL-4/IL-13) inhibitors and Janus kinase (JAK) inhibitors in atopic dermatitis." (PMID 39202657, 2024).
atopic dermatitis (continued). "The objective of this review was to evaluate the efficacy of IL-4/IL-13 inhibitors and JAK inhibitors concerning the restoration of skin barrier abnormalities in atopic dermatitis." (PMID 39202657, 2024). "Materials and Methods: A comprehensive review of the literature was conducted, focusing on studies that assess the use of IL-4/IL-13 inhibitors and JAK inhibitors for atopic dermatitis." (PMID 39202657, 2024). "This review mainly summarizes the beneficial effects of IL-4/IL-13 inhibitors, and comparatively less of JAK inhibitors, on skin barrier function in atopic dermatitis." (PMID 39202657, 2024). "Here, we investigated the effect of histamine in an atopic dermatitis skin milieu sustained by TH2 cytokines (IL-4, IL-13 and IL-31), using human keratinocytes and full-thickness skin models with a developed epidermal layer." (PMID 36615633, 2023). "Dupilumab is a monoclonal antibody that acts as a dual inhibitor to IL-4 and IL-13 cytokine signaling and has been approved by the FDA since 2017 for the treatment of atopic dermatitis with subsequent indications for asthma and nasal polyps." (PMID 35434724, 2022). "Nasal drug delivery is a form of peripheral administration and IL-13 is a pleiotropic type 2 cytokine that contributes to eosinophil chemotaxis in eosinophilic esophagitis (EOE) and atopic dermatitis (AD)." (PMID 35578342, 2022). "Second, for the treatment of atopic dermatitis, C. asiatica significantly reduced the inflammation response (TNF-α ↓, IL-1β ↓, IL-8 ↓, IL-4 ↓, and IL-13 ↓), and also the local immune response (IgE ↓)." (PMID 33013406, 2020). "Dupilumab, a dual-acting drug blocking both IL-4 and IL-13 function was approved by the Food and Drug Administration (FDA) and European Medicines Agency (EMA) in 2017 for use in atopic dermatitis." (PMID 30759882, 2019). "In a mouse model of atopic dermatitis induced by topical application of Calcipotriene (a synthetic Vitamin D3 derivative), ILC2-derived IL-5 and IL-13 were reported to play an important role in promoting the disease development." (PMID 28271445, 2017). "Combined effects of IL-13 or CD14 genetic variations and delivery mode on the development of atopic dermatitis (AD) at 1 year of age." (PMID 24848505, 2014). "IFN-γ and IL-13 concentrations were lower in treated dogs than in healthy dogs and untreated dogs, whereas IL-31 concentrations were higher in dogs with atopic dermatitis than in healthy dogs, regardless of treatment status." (PMID 42071951, 2026). "For example, in atopic dermatitis, combining a JAK inhibitor with dupilumab (an IL‐4/IL‐13 inhibitor) may enhance disease control while reducing the dosage requirements of each agent, thereby minimizing adverse effects." (PMID 40536117, 2025). "(2016) reported that IL‐13 concentrations were significantly increased in dogs with atopic dermatitis, while IL‐4 did not change." (PMID 38648253, 2024). "To get insight into the mechanism of the decline in OBP2A expression in atopic dermatitis lesional skin, we measured changes in OBP2A expression in human keratinocytes treated with type 2 cytokine IL-4 or IL-13, known to be involved in the pathogenesis of atopic dermatitis." (PMID 39502293, 2024). "By contrast, atopic dermatitis and Th2-related genes, including Il4, Il5, Il13 and Il31 were lowly expressed or not detected at all, and other atopic dermatitis-related transcripts (Ccr4, Ccl17, Ccl24) were not significantly differentially expressed." (PMID 38528069, 2024). "Considering all the results in the experimental model and in dogs spontaneously affected with atopic dermatitis, some similarities have been shown for TH2 cytokines with a significant increase of IL-4 and IL-13 in sensitized and lesional sites compared with control sites." (PMID 39852879, 2024).